PTCH2 (patched 2)
Description:
Negative regulator of the smoothened signaling pathway, which acts as a receptor for hedgehog (SHH, IHH and DHH) morphogens. In absence of hedgehog, acts as an inhibitor of smoothened protein (SMO) by preventing SMO access to cholesterol: mechanistically, acts as a cholesterol transporter, which depeletes cholesterol from the outer leaflet of plasma membrane, thereby preventing cholesterol-binding to the extracellular CRD region of SMO. Hedgehog-binding inhibits PTCH1 cholesterol transporter activity, promoting SMO activation by cholesterol and transduction of the smoothened signaling pathway. Molecular mechanism governing cholesterol transport are still unclear: may move cholesterol from the outer to the inner leaflet of the membrane in exchange for potassium or sodium ion export in the opposite direction (By similarity). In contrast to PTCH1 ortholog, PTCH2 is not essential for viability and plays a more limited role. Plays a role in epidermal homeostasis in mature skin (By similarity). Plays a role in the control of cellular growth.
Synonyms: PTC2; SLC65B2
Tractability: Antibody: UniProt predicts a signal peptide or a membrane-spanning region; its Gene Ontology location is reachable by antibodies, with medium confidence; the Human Protein Atlas places it where antibodies can reach.
Gene: Protein-coding gene on chromosome 1 (44,819,154 to 44,843,253, reverse strand). Ensembl gene ENSG00000117425.
Subcellular location: Cell membrane; Cell projection, cilium membrane
Subcellular location (Human Protein Atlas): Plasma membrane; Nucleoli
Pathways (Reactome):
Signal Transduction: Class B/2 (Secretin family receptors); GLI proteins bind promoters of Hh responsive genes to promote transcription
Gene Ontology:
Molecular function: hedgehog family protein binding; smoothened binding; hedgehog receptor activity; intramembrane lipid transporter activity
Biological process: regulation of cell growth; negative regulation of smoothened signaling pathway; lipid translocation
Cellular component: plasma membrane; non-motile cilium membrane; ciliary membrane; membrane
Genetic constraint (gnomAD): Loss-of-function variants: 96 observed, 127.14 expected, observed/expected ratio (o/e) 0.76, 90% interval 0.64 to 0.89. The upper end of that interval is the gene's LOEUF score, 0.89, which puts it in group 3 of 6, group 1 being the genes least tolerant of losing a copy. Missense variants: 1,379 observed, 1,616.8 expected, observed/expected ratio (o/e) 0.85, 90% interval 0.81 to 0.89. Synonymous variants: 615 observed, 687.26 expected, observed/expected ratio (o/e) 0.89, 90% interval 0.84 to 0.96.
Gene-disease validity (ClinGen):
ClinGen rates the evidence that PTCH2 causes each of these diseases.
nevoid basal cell carcinoma syndrome (autosomal dominant): Limited. A rare hereditary disorder due to autosomal dominant transmission with hamartosis characterized by multiple early-onset basal cell carcinoma (BCC), multiple jaw keratocysts and skeletal abnormalities.
Homologues: Orthologues: chimpanzee PTCH2 (99% identical), rabbit PTCH2 (94% identical), dog PTCH2 (93% identical), pig PTCH2 (92% identical), rat Ptch2 (90% identical), mouse Ptch2 (89% identical), guinea pig PTCH2 (87% identical), tropical clawed frog ptch2 (66% identical), zebrafish ptch2 (65% identical), Drosophila melanogaster ptc (36% identical), Caenorhabditis elegans ptc-1 (35% identical), Caenorhabditis elegans ptr-17 (13% identical), and 3 more. Paralogues in human: PTCH1 (55% identical), NPC1L1 (20% identical), NPC1 (20% identical), PTCHD3 (15% identical), DISP3 (14% identical), PTCHD1 (13% identical), DISP2 (13% identical), DISP1 (12% identical), PTCHD4 (11% identical), SCAP (10% identical).
Diseases named in the same sentence as PTCH2 in open-access papers:
PTCH2 is named in the same sentence as 39 diseases in open-access papers, as found by Europe PMC text mining. Sharing a sentence is not in itself a finding about the gene and the disease. The quoted sentences say what the papers report.
Gorlin syndrome (24 papers, 2015 to 2025). "Gorlin syndrome can also be caused by mutations in the patched 2 (PTCH2) gene and suppressor of fused (SUFU) gene as well." (PMID 40385857, 2025). "They reported the presence of simultaneous mutations in PTCH1 and PTCH2 in patients with Gorlin syndrome." (PMID 37762102, 2023). "Other rare causative genes have also been identified in Gorlin syndrome including PTCH2 and SUFU encoding for patched 2 and suppressor of fused homolog proteins, respectively." (PMID 31979112, 2020). "Previously, studies suggested that both PTCH1 and PTCH2 are causative genes of Gorlin syndrome and holoprosencephaly." (PMID 32864857, 2020). "As PTCH2 is a well‐known pathogenic gene of Gorlin syndrome, P37 and P50 received careful physical examination and pathological biopsy to exclude this possibility." (PMID 32864857, 2020). "Recently, mutations in Suppressor of fused homolog (SUFU) or PTCH2 were reported in patients with Gorlin syndrome." (PMID 28915250, 2017). "In fact, SUFU and PTCH2 mutations have been reported as another possible causative genes of Gorlin syndrome." (PMID 28915250, 2017). "However, patients with mutated PTCH2 displayed milder phenotypes of Gorlin syndrome when compared against PTCH1 and SUFU-related diseases." (PMID 36937440, 2023). "Gorlin syndrome, or basal cell nevus syndrome, is a hereditary disease related to the mutations (more than 100 gene mutations have been reported) of patched 1, patched 2 and PTCH2, and SUFU genes, characterized by systemic and diverse developmental abnormalities and neoplastic lesions." (PMID 33809659, 2021). "PTCH2 was reported to be a rare causative gene for Gorlin syndrome." (PMID 28915250, 2017). "The most common BCC syndrome, Gorlin syndrome or basal cell nevus syndrome, is an autosomal dominant (AD) disorder most frequently associated with PTCH1 mutation, while PTCH2 and SUFU are less commonly implicated." (PMID 40290801, 2025). "Recent studies have identified pathogenic mutations in the hedgehog pathway, especially in “patched” (PTCH1 and PTCH2) genes, in Gorlin syndrome." (PMID 38927872, 2024). "The gene panel analyzed the PTCH1, PTCH2, SUFU, and SMO genes, all of which are associated with Gorlin syndrome." (PMID 37762102, 2023). "Germline inactivation of one copy of the Hh receptor Patched 1 (PTCH1) gene and, more rarely, of PTCH2, or of Suppressor of Fused (SUFU), followed by the somatic loss of the second allele results in Gorlin syndrome that are frequently observed in BCC patients." (PMID 35804983, 2022). "Previously, we observed via exome sequence analysis that two out of four patients with Gorlin syndrome exhibited mutations in both the PTCH1 and PTCH2 genes." (PMID 34674729, 2021). "We previously reported the presence of mutations in PTCH2 and BOC, alongside PTCH1, in four unrelated patients with Gorlin syndrome patient via exome sequencing." (PMID 34674729, 2021). "Rare causes are PTCH2 and SMO mutations: a missense mutation in PTCH2 was disclosed in a Chinese family, and a SMO mutation in a single case with a segmental basal cell nevus syndrome." (PMID 29552546, 2018). "Aberrations in Hh pathway genes PTCH1, PTCH2, and SUFU are associated with nevoid basal cell carcinoma syndrome (NBCCS; also known as Gorlin syndrome), which predisposes patients to SHH-MB, basal cell carcinoma, and skeletal abnormalities." (PMID 29050204, 2017). "Furthermore, recently PTCH2 and possibly also SMO mutations have been described as a potential cause for Gorlin syndrome associated medulloblastoma." (PMID 34888241, 2021). "First, we investigated whether mutations were located in either the PTCH2 or SUFU genes, since both were reported as rare causative genes of Gorlin syndrome." (PMID 28915250, 2017). "In addition, mutations in rare causative genes other than PTCH1, such as PTCH2 and SUFU, have also been detected in individuals suffering from Gorlin syndrome." (PMID 26544948, 2015).
Gorlin syndrome (continued). "Recently, potentially disease causing heterozygous PTCH2 variants have been identified in patients with a milder Gorlin associated phenotype and controversially discussed but this gene has not yet been included in routine testing for Gorlin syndrome." (PMID 34888241, 2021). "In all these reports, the patients did not exhibit a typical Gorlin syndrome phenotype and Smith and Evans highlighted the uncertain pathogenetic significance of the described mutations, prompting that PTCH2 might not be a bona fide Gorlin syndrome predisposition gene." (PMID 37947611, 2023). "ELP1 and GPR161 therefore join PTCH2 as potential candidate genes for Gorlin syndrome that can be dismissed on their population frequencies and, for PTCH2 and GPR161, their absence in Gorlin syndrome kindreds." (PMID 36961676, 2023). "A number of case/family reports have proposed PTCH2 as a putative Gorlin Syndrome (GS) gene, but evidence to support this is lacking." (PMID 34170463, 2022). "One male patient met four of the major criteria of the Gorlin syndrome, with the existence of PTCH1 and PTCH2 mutations in his normal oral tissue." (PMID 34674729, 2021).
medulloblastoma (9 papers, 2008 to 2025). A malignant, invasive embryonal neoplasm arising from the cerebellum. "Using single-stranded conformational polymorphism analysis, a truncating mutation of the PTCH2 gene was identified in a patient with medulloblastoma." (PMID 37504252, 2023). "In the medulloblastoma, we observed 45 tumor‐specific pathogenic variants in 35 CNS tumor‐related genes, including PTCH1, PTCH2, and SMO, which are frequently altered in medulloblastomas." (PMID 40880425, 2025). "Somatic mutations in PTCH2 have been implicated in the development of BCC1 (OMIM 605462) and medulloblastoma (OMIM 155255)." (PMID 37504252, 2023). "High PTCH2 expression has also been observed in familial and sporadic basal cell carcinoma, and PTCH2 is considered to be an important gene in murine medulloblastoma tumorigenesis." (PMID 34573430, 2021). "However, mutations in others genes such as Patched 2 (PTCH2), Smmothened (SMO) and Sonic hedgehog (SHH) have been reported in isolated cases of basal cell carcinoma and medulloblastoma." (PMID 21266031, 2011). "Similarly, over-expression of associated network clusters enriched for SHH pathway members, GLI1, PTCH1 and PTCH2, was exclusive to human SHH medulloblastoma, and expression levels were significantly higher than in CD133+ NSCs, NPCs and all other controls used in this study." (PMID 25412507, 2014).
basal cell carcinoma (7 papers, 2011 to 2023). A carcinoma involving the basal cells. "The exact contribution of Ptch2 to an established cancer type such as basal cell carcinoma (BCC) has, however, remained unclear, despite clinical data that suggest a tumor suppressor function." (PMID 29869097, 2018).
pancreatic cancer (5 papers, 2011 to 2021). "PDS5B alleviates cell viability, migration, and invasion via promoting Ptch2 expression in pancreatic cancer cells." (PMID 34226509, 2021). "The data demonstrate that the components of SHH signaling pathway, including the ligand (Shh), the signaling molecules (Patched-1, Patched-2 and Smoothened) and effectors (Gli1, and Gli2) are expressed in human pancreatic cancer cell lines and pancreatic CSCs." (PMID 22087285, 2011). "The components of Sonic Hh signaling pathway, including the ligand (SHh), the signaling molecules (Patched-1, Patched-2 and Smoothened) and effectors (Gli1, and Gli2) are aberrantly expressed in human pancreatic cancer cell lines and pancreatic cancer stem cells." (PMID 26369833, 2015). "Of particular interest, Smoothened-dependent GDC-0449 treatment of pancreatic CSCs markedly inhibited expressions of SHH receptors (Patched-1, Patched-2 and Smoothened) and effectors (Gli1 and Gli2), thereby showing potential for therapeutic application for treatment of pancreatic cancer." (PMID 22087285, 2011). "Gedunin treated pancreatic cancer cells were effectively downregulated PTCH1, PTCH2, Gli1, SUFU and Shh proteins involved in Hedgehog/Gli signaling pathway." (PMID 26988754, 2017).
glioblastoma (4 papers, 2015 to 2024). The most malignant astrocytic tumor (WHO grade IV). "For instance, the testis-specific expression of Desert Hedgehog (Dhh) and Ptch2 and their role in glioblastoma-endothelium crosstalk hints to this possibility." (PMID 29869097, 2018). "In human primary glioblastoma initiating cells, sonidegib reduces levels of GLI1, GLI2, PTCH1, and PTCH2 messenger ribonucleic acid (RNA) and protein, as well as GLI1 and GLI2 translocation into the nucleus." (PMID 32973971, 2020). "Collectively, these results unveil a role for DHH in exacerbated tumor angiogenesis and permeability, which can ultimately favor glioblastoma growth, and thus place the DHH/Ptch2 nexus as a potential candidate for therapeutic intervention." (PMID 26635611, 2015). "Collectively, our data unveil a role for DHH in exacerbated tumor angiogenesis and permeability, which may ultimately favor glioblastoma growth, and thus place the DHH/Ptch2 nexus as a molecular target for novel therapies." (PMID 26635611, 2015).
alopecia (3 papers, 2019 to 2022). Hair loss usually from the scalp. "Ptch2 plays redundant roles during embryogenesis, and the phenotypes of Ptch2 mutants are manifested at postnatal stages; the mutation causes alopecia (hair loss) and epidermal hyperplasia." (PMID 31781166, 2019). "Previous studies have shown that most of the Ptch2 hypomorph mutants display a normal skin phenotype, although some males can develop alopecia, ulcerations, or epidermal hyperplasia later in life." (PMID 35574464, 2022).
bladder cancer (3 papers, 2016 to 2018). "High expression of PTCH2 was associated with a poorer survival in patients with bladder cancer." (PMID 28482871, 2017). "Importantly, silencing the PTCH2 gene could weaken the autophagy induction, suggesting the involvement of Hh signaling in capsaicin-induced autophagy in bladder cancer cells." (PMID 30081498, 2018).
endometriosis (3 papers, 2017 to 2018). The growth of functional endometrial tissue in anatomic sites outside the uterine body. "PTCH2 is a membrane receptor, member of the Hedgehog signaling pathway, and has been associated with proliferation-related disorders such as endometriosis and ovarian carcinoma, playing a role as a tumor suppressor gene." (PMID 29118976, 2017). "It was reported that OCCC-associated endometriosis already harbors aberrant gene expression, such as altered expressions of eEF1A2, PTCH2, PPP1R14B, and XRCC5, which may not be found in endometriosis tissue in the absence of cancer." (PMID 29941051, 2018).
meningioma (3 papers, 2021 to 2024). A generally slow growing tumor attached to the dura mater. "Patched 2 receptor gene (PTCH2), a tumor suppressor in the Sonic Hedgehog (SHH) signaling pathway, appeared to be the most significantly upregulated gene in this group, implying that decreased expression of PTCH2 due to chr1p loss may result in increased aggressiveness of NF2-2 meningiomas." (PMID 36937440, 2023). "Aberrant signaling in the sonic hedgehog (SHH) pathway caused by mutations in PTCH1, PTCH2, and SUFU genes, located at 9q22.32, 1p34.1, and 10q24.32, respectively, with PTCH1 being the most common, increases the risk of meningioma development." (PMID 33801089, 2021). "Patients with SUFU mutations are more likely to develop meningiomas compared to PTCH1 or PTCH2 mutations even with the absence of PTCH mutation, which have been found in families with hereditary multiple meningiomas." (PMID 33801089, 2021).
skin tumors (3 papers, 2018 to 2022). "However, Ptch2 deficiency does exacerbate the skin tumor phenotype in partially Ptch1 deficient mice by deregulating epidermal lineage differentiation, and it has been found that the absence of both paralogs affects skin maintenance." (PMID 29869097, 2018).
ovarian carcinoma (2 papers, 2017 to 2025). A malignant neoplasm originating from the surface ovarian epithelium. "SHH, HHAT, PTCH1, and PTCH2 overexpression further improved the survival rates of ovarian cancer patients, particularly when optimal debulking was possible." (PMID 40565349, 2025). "Using the database Kaplan–Meier plotter, which includes the gene expression and survival data of 1565 ovarian cancer patients, higher expression levels of the genes SHH, PTCH1, PTCH2, and GLI1 displayed better survival correlations, while GLI, GLI3, and SUFU correlated with adverse outcomes." (PMID 40565349, 2025). "To assess their potential prognostic value, we analyzed the correlation between the expression levels of the following eight components of the Hedgehog signaling pathway on the progression-free (PFS) and overall survival (OS) in ovarian cancer: SHH, GLI1, GLI2, GLI3, PTCH1, PTCH2, HHAT, and SUFU." (PMID 40565349, 2025).
lipoma (1 paper, 2026). A benign, usually painless, well-circumscribed lipomatous tumor composed of adipose tissue. "Our findings demonstrate that loss of Ptch2 triggers lipoma formation and adipogenic transcriptome reprogramming, highlighting its essential role in maintaining adipose tissue homeostasis." (PMID 41681386, 2026).
lung carcinoma (1 paper, 2019). "We next analyzed the expression levels of canonical SHH signaling components—such as PTCH1, PTCH2, SMO, SUFU, and GLI1 proteins—in cultured human lung cancer cells (H1299, A549, HCC827, and H1975) and normal human lung fibroblasts (MRC-9 and WI38) by western blot analysis." (PMID 31783569, 2019).
myeloproliferative neoplasm (1 paper, 2020). A clonal hematopoietic stem cell disorder, characterized by proliferation in the bone marrow of one or more of the myeloid (i.e., granulocytic, erythroid, megakaryocytic, and mast cell) lineages. "In addition, in myeloproliferative neoplasms, the loss of PTCH2, and, consequently, Shh pathway activation, it was shown to improve tumor resistance to Fluorouracil (5-FU) treatment." (PMID 33271924, 2020).
osteosarcoma (1 paper, 2017). A usually aggressive malignant bone-forming mesenchymal neoplasm, predominantly affecting adolescents and young adults. "The results showed that knockdown of CNOT1 significantly inhibited the expression of GLI1, PTCH1, and PTCH2 in osteosarcoma cells." (PMID 28188704, 2017).
serous ovarian cancers (1 paper, 2020). "This analysis revealed an enrichment of SHH pathway genes, including GLI1, GLI2, HHIP, PTCH1, and PTCH2, in SSTs as compared to high-grade serous ovarian cancers and other sex cord-stromal tumors." (PMID 31896750, 2020).